LNCARSR (lncRNA regulator of Akt signaling associated with HCC and RCC)
Synonyms: lnc-TALC
Gene: Long non-coding RNA gene on chromosome 9 (79,505,801 to 79,571,041, reverse strand). Ensembl gene ENSG00000233086.
Diseases named in the same sentence as LNCARSR in open-access papers:
LNCARSR is named in the same sentence as 16 diseases in open-access papers, as found by Europe PMC text mining. Sharing a sentence is not in itself a finding about the gene and the disease. The quoted sentences say what the papers report.
renal cell carcinoma (22 papers, 2016 to 2025). "It is important to note that lncARSR has been found to cause resistance to sunitinib and adriamycin in renal cell carcinoma and osteosarcoma." (PMID 36980210, 2023). "In addition, lncARSR levels in plasma and tumor tissues were associated with sunitinib response in individuals with renal cell carcinoma." (PMID 35159299, 2022). "Exosomal lncARSR released from renal cell carcinoma (RCC) cells promotes sunitinib resistance by binding to miR-34 and miR-449." (PMID 36839784, 2023). "LncARSR was firstly found in renal cell carcinoma (RCC) cells, and was related with resistance to sunitinib in RCC patients." (PMID 33390845, 2021). "In renal cell cancer, levels of plasma lncARSR is higher than those of healthy blood donors, lncARSR levels decreased after tumor resection and were elevated upon tumor relapse." (PMID 27358717, 2016). "Additionally, several studies have found that lncARSR plays an oncogene role in various cancers, including renal cell carcinoma, colorectal cancer, bladder cancer, and non-small-cell lung cancer." (PMID 36980210, 2023). "Also, the levels of lncARSR found in the plasma and tumor tissues correlated with Sunitinib response in renal cell carcinoma patients." (PMID 32384712, 2020). "Targeted blockade of lncARSR or the use of AXL/c-MET inhibitors may aid in treating renal cell carcinoma that is resistant to sunitinib." (PMID 29552328, 2018). "In renal cell carcinoma, sunitinib-resistant cells highly express lncARSR, which in turn is packaged in RCC EVs to be shuttled to recipient cells." (PMID 33317058, 2020). "For example, lncARSR, an lncRNA highly expressed in sunitinib-resistant renal cell carcinoma (RCC) cells, can be packaged into exosomes and transmitted to sunitinib-sensitive RCC cells, leading to the dissemination of sunitinib resistance." (PMID 31273188, 2019). "lncARSR may serve as an effective molecular marker and intervention target to improve the therapeutic efficacy of sunitinib in renal cell carcinoma and provide a new approach and perspective for the individualized target therapy of renal cell carcinoma." (PMID 29552328, 2018). "For instance, Exosomal lncARSR promotes M2 macrophage polarization via STAT3 activation, advancing renal cell carcinoma." (PMID 40761779, 2025). "LncARSR is an RNA activated in sunitinib-resistant renal cell carcinoma (RCC)." (PMID 39135913, 2024). "In a separate study, it is found that lncARSR facilitates the expression of AXL and c-MET by competitively binding miR-34/miR-449, thereby enhancing resistance to sunitinib in renal cell carcinoma cells." (PMID 38100482, 2023). "Exosome-transmitted lncARSR functions as a sponge of miR-34/miR-449 to induce c-MET and AXL expression and mediates sunitinib resistance in renal cell carcinoma." (PMID 33154765, 2020). "For example, lncARSR promotes sunitinib resistance via competitively binding miR‐34/miR‐449 to facilitate AXL and c‐MET expression in renal cell carcinoma (RCC) cells, and intercellular transfer of lncARSR by exosomes disseminated sunitinib resistance." (PMID 32578911, 2020). "Furthermore, the EV-mediated intercellular transfer of lncARSR enhanced AXL and c-MET expression in renal cell carcinoma cells, which improved sunitinib resistance by competitive interaction with miR-34/miR-449." (PMID 35159299, 2022). "Additionally, EV-mediated intercellular transfer of lncARSR (which promoted Sunitinib resistance through competitive binding with miR-34/miR-449) increased AXL and c-MET expression in renal cell carcinoma cells." (PMID 32384712, 2020). "Exosomes containing lncARSR secreted from renal cell carcinoma (RCC) were found to promote M2 polarization by activating the STAT3 pathway, thus favoring RCC progression." (PMID 36612282, 2022).
renal carcinoma (18 papers, 2017 to 2025). A carcinoma arising from the epithelium of the renal parenchyma or the renal pelvis. "Exosomes secreted by renal carcinoma cells will spread to other renal carcinoma cells and eventually cause resistance to sunitinib via transporting lncARSR." (PMID 36699697, 2022). "For example, lncARSR in sEVs promoted sunitinib resistance in renal cancer in a ceRNA-dependent manner." (PMID 39121006, 2024). "Remarkably, lncARSR was identified as a predictive marker for poor response in patients with renal cancer, with emerging data suggesting its exosomal release from therapy-resistant cells, thereby conferring treatment resistance." (PMID 38790894, 2024). "In renal cancer, lncARSR functions as an oncogene, and exosomal lncARSR can transfer sunitinib resistance from sunitinib-resistant cells to sunitinib-sensitive cells." (PMID 34819615, 2021). "In the previous reports, a series of lncRNAs (such as CTBP1-AS in PCa, lncARSR in renal cancer, and NKILA in breast cancer were reported to play key roles in regulating cancer progression." (PMID 33082888, 2020). "It is suggested that lncARSR acts an oncogene and plays a critical role in the development of renal cancer, hepatocellular carcinoma and ovarian cancer 18-20." (PMID 31892841, 2020). "In renal cancer, lncARSR functions as miRNA sponge to competitively bind with miR-34 and miR-449, which can up-regulate AXL/c-MET and activate STAT3, AKT, and ERK signaling." (PMID 31892841, 2020). "For example, exosomes released from sunitinib-resistant cells transferred lncARSR to sensitive cells, which induced sunitinib resistance in renal cancer." (PMID 30285771, 2018). "By competing binding with miR‐34/miR‐499, lncARSR could increase sunitinib resistance in renal cancer." (PMID 39999286, 2025). "Qu showed that exosome-transmitted lncARSR promoted sunitinib resistance in renal cancer." (PMID 33627162, 2021). "Thus, lncARSR can serve as a therapeutic target for renal cancer with sunitinib resistance." (PMID 34819615, 2021). "Exosome from sunitinib-resistant renal cancer cells could transfer lncARSR (lncRNA activated in RCC with sunitinib resistance) to sensitive cells, in which LncARSR competes with miR-34 and miR-449, promotes AXL and c-MET expression, reactivates RTKs, and mediates drug resistance." (PMID 32242003, 2020). "In another excellent study, lncARSR (lncRNA Activated in RCC with Sunitinib Resistance) was found encapsulated into exosomes and conferred Sunitinib resistance in renal cancer by acting as a competing endogenous RNA25." (PMID 28361920, 2017). "Likewise exosome-transmitted lncARSR can promote sunitinib resistance by binding miR-34/miR-449 to facilitate AXL and c-MET expression in renal cancer, acting as a competing endogenous RNA." (PMID 32754302, 2020).
hepatocellular carcinoma (3 papers, 2019 to 2022). A malignant tumor that arises from hepatocytes. "LncARSR is responsible for LCSC expansion by rising the dedifferentiation of hepatoma cells and increasing the self-renewal, progression, and tumorigenesis capacity of LCSCs." (PMID 36359888, 2022). "LncARSR overexpression is seen in CD24+/CD133+ LCSCs as well as in hepatoma spheres augmented with CSC." (PMID 36359888, 2022). "LncARSR was up-regulated in liver cancer stem cells (CSCs) and promoted hepatocellular carcinoma cells dedifferentiation and liver CSCs separation by modulating STAT3 signaling." (PMID 31892841, 2020).
liver cancer (3 papers, 2020 to 2023). An epithelial or non-epithelial malignant neoplasm that arises from the liver. "In terms of pathological phenomena, the expression of lncARSR can reliably reflect the course of liver cancer through its different stages." (PMID 36980210, 2023). "Importantly, all current studies on lncARSR in the treatment of liver cancer resistance have focused on doxorubicin, which means that the detection of lncARSR is highly specific and can be used to identify whether patients are suitable for treatment with doxorubicin." (PMID 36980210, 2023). "LncARSR, as one of the up-regulated lncRNAs in NAFLD, was proved to promote liver cancer stem cell expansion and HCC differentiation." (PMID 32169080, 2020).
osteosarcoma (3 papers, 2020 to 2022). A usually aggressive malignant bone-forming mesenchymal neoplasm, predominantly affecting adolescents and young adults. "The present study found lncARSR expression raised in ADM-resistant osteosarcoma cells and aimed to illuminate the mechanisms underlying lncARSR increment and ADM resistance of osteosarcoma." (PMID 32404870, 2020). "Consistent with this, lncARSR knockdown in these ADR-resistant osteosarcoma cells facilitated cell rhodamine 123 retention and apoptosis." (PMID 36059609, 2022). "Our study extended the knowledge about the involvement of lncARSR in chemoresistance and provided a novel therapeutic target for treating refractory osteosarcoma." (PMID 32404870, 2020). "To evaluate the potential effects of si-lncARSR plus ADM on tumor growth, we subcutaneously injected U2OS/ADM cells to BALB/c nude mice to generate ADM-resistant osteosarcoma mouse models." (PMID 32404870, 2020).
colorectal cancer (2 papers, 2021). A primary or metastatic malignant neoplasm that affects the colon or rectum. "In addition, low expression of miR-34a-5p results in the development of colorectal cancer by promoting the migration of colorectal cancer cells, with LncARSR promoting invasion and metastasis of colorectal cancer by sponging miR-34a-5p." (PMID 34471485, 2021).
ovarian carcinoma (2 papers, 2019 to 2021). A malignant neoplasm originating from the surface ovarian epithelium. "In ovarian cancer, lncARSR interacts with HuR, upregulates β-catenin expression, and then activates Wnt/β-catenin signaling pathway." (PMID 31053733, 2019).
bladder cancer (1 paper, 2020). "In conclusion, our study indicated that lncARSR plays a critical regulatory role in Bca cells and lncARSR may serve as a potential diagnostic biomarker and therapeutic target for bladder cancer." (PMID 31892841, 2020). "In this study, we discovered that lncARSR was significantly up-regulated in bladder cancer." (PMID 31892841, 2020). "However, the clinical significance and molecular mechanism of lncARSR in bladder cancer (Bca) remains unknow." (PMID 31892841, 2020). "Our results suggested that lncARSR acts as a nature miRNA sponge to positively regulate SOX4 expression through sponging miR-129-5p and subsequently promotes the proliferation, migration and invasion of Bca cells, thus playing an oncogenic role in the progression of bladder cancer." (PMID 31892841, 2020).
Hypertension (1 paper, 2019). The presence of chronic increased pressure in the systemic arterial system. "Intriguingly, our results imply that genetic variants of lncARSR can be protective factors among patients with BMI > 24, without hypertension and without family history of cancer." (PMID 31038847, 2019).
Insulin resistance (1 paper, 2020). Increased resistance towards insulin, that is, diminished effectiveness of insulin in reducing blood glucose levels. "Therefore, the effect of lncARSR/YAP1/IRS2/AKT axis on NAFLD by regulating insulin resistance needs further elaboration." (PMID 32169080, 2020).
tumor (11 papers, 2016 to 2022). "Our results reveal that RCC derived exosomes promote tumor growth and macrophage polarization by carrying lncARSR cargo." (PMID 35637970, 2022). "The roles of exosomes and its cargo lncARSR in macrophage polarization and tumor development in RCC are still poorly understood." (PMID 35637970, 2022). "Overexpression of lncARSR induced phenotypic and functional changes of macrophages in vitro and promoted tumor growth in vivo, while knockdown of lncARSR by siRNA disrupted the exosomes-mediated macrophage polarization." (PMID 35637970, 2022). "Increased expression of lncARSR was correlated with high histological grade and large tumor size in Bca patients." (PMID 31892841, 2020). "In our study, we presented that lncARSR was significantly up-regulated in Bca tissues compared with corresponding non-tumor tissues in total of 62 Bca patients." (PMID 31892841, 2020). "We observed the diminishment of lncARSR inhibited tumor growth and conquered ADM resistance in vivo." (PMID 32404870, 2020). "In general, our data reveals that lncARSR is a powerful tumor biomarker for the diagnosis and treatment of Bca." (PMID 31892841, 2020). "The average level of lncARSR was higher in ccRCC tumours than adjacent non-tumour tissues determined by quantitative PCR with reverse transcription (qRT–PCR) and in situ hybridization (ISH)." (PMID 27886176, 2016). "In vivo limiting dilution assay revealed that suppression of lncARSR significantly reduced tumour incidence and T-IC frequency consistent with the cell culture studies." (PMID 27886176, 2016). "In tumour cells isolated from primary ccRCC tissues, pearson correlation analysis revealed that lncARSR levels were positively correlated with the expression of CD105 and CD133." (PMID 27886176, 2016). "In addition, similar to miR-210, the levels of lncARSR decreased after tumor resection and were elevated again upon tumor relapse, linking its production to disease progression." (PMID 35052770, 2021). "In addition, increased expression of lncARSR was positively correlated with higher histological grade and larger tumor size." (PMID 31892841, 2020). "Though there is a lack of experimental evidence to elucidate the biological process how the SNPs of lncARSR participate in the tumor initiation and progression, our study provides a feasible basis for further investigation which has been applied to other lncRNAs." (PMID 31038847, 2019). "Notably, lncARSR expression was elevated in poorly differentiated ccRCC tumours compared with well-differentiated tumours, prompting a putative role of lncARSR in renal T-ICs." (PMID 27886176, 2016). "Hence, our study revealed that lncARSR may become a powerful tumor biomarker for the diagnosis and treatment of Bca." (PMID 31892841, 2020). "After validating that lncARSR can promote macrophage polarization in vitro, we next examined its roles in vivo using the RCC orthotopic tumor model." (PMID 35637970, 2022). "Together, RCC-derived exosomes facilitate the development of tumor through inducing macrophage polarization via transferring lncARSR, suggesting that RCC-derived exosomes, lncARSR and STAT3 are the potential therapeutic targets for treatment of RCC." (PMID 35637970, 2022). "LncARSR knockdown suppresses renal tumor-initiating cell self-renewal, tumorigenicity and metastasis, and forced lncARSR over-expression enhances RCC cell tumor-initiating function." (PMID 33593347, 2021). "To verify the correlation between lncARSR and YAP activity in clinical samples, we examined the RNA levels of lncARSR and YAP target genes in 52 human ccRCC tumour specimens." (PMID 27886176, 2016). "We have clearly demonstrated that lncARSR can promote macrophage polarization and RCC tumor growth." (PMID 35637970, 2022). "We found that the tumor volume of nude mice was significantly increased and the expression levels of F4/80, CD206 and Ki67 were significantly increased by immunohistochemistry in the lncARSR overexpression group." (PMID 35637970, 2022).
tumor (continued). "Consistent with our study, several other studies had reported that lncRNAs promote tumor angiogenesis or sunitinib resistance in RCC, including HOTAIR and lncARSR, supporting that lncRNAs may provide new targets for therapy and predictive biomarkers for anti-angiogenesis therapy response in RCC." (PMID 35562342, 2022).
cancer (7 papers, 2018 to 2022). A tumor composed of atypical neoplastic, often pleomorphic cells that invade other tissues. "Recently, lncARSR was regarded as a potential biomarker and got involved in the progression of different cancers." (PMID 31892841, 2020). "lncARSR is highly expressed in sunitinib-resistant RCC cells, and cancer cells can disseminate survival skills to other recipient cells via exosomes containing lncARSR." (PMID 29678180, 2018). "Future work will be conducted to investigate whether reduction in lncARSR or STAT3 levels might inhibit other cancer progression by boosting the immune response." (PMID 35637970, 2022). "LncARSR was up-regulated in 63% (39/62) of cancer tissues compared with normal tissues (Figure." (PMID 31892841, 2020). "As a novel long noncoding RNA, lncARSR has been confirmed to participate in the pathophysiological process of cancers, but there are no publications focusing on genetic roles of cancer‐related polymorphisms." (PMID 31038847, 2019).
infection (1 paper, 2020). The state of being infected such as from the introduction of a foreign agent such as serum, vaccine, antigenic substance or organism. "In addition, silencing lncARSR reduced IRS expression and phosphorylation level of AKT but increased phosphorylation level of YAP1 in HepG2 cells, which was further promoted by additional infection with YAP1S127D." (PMID 32169080, 2020).
LNCARSR also shares sentences with these, for which no sentence is quoted: breast carcinoma (1 paper); kidney cancer (1); metastatic disease (1).